CD44 (CD44 molecule (IN blood group))
Diseases named in the same sentence as CD44 in open-access papers (continued):
Sharing a sentence is not in itself a finding about the gene and the disease.
tumor (continued). "Remarkably, miR-141 overexpression via lenti-141 infection significantly suppressed xenograft tumour growth in CD44+ LAPC9 and in bulk DU145 and PPC-1 cells." (PMID 28112170, 2017). "The interaction between HA and CD44 regulates development, inflammation, T cell recruitment and activation, tumor growth, and metastasis." (PMID 28091588, 2017). "Namely alternative splicing leads to a lengthening of CD44-extracellular domain, promoting its greater interaction with HA and tumor metastasis." (PMID 28622715, 2017). "Differential gene expression analysis generated 128 genes that segregated bulk tumor regions from EPCAM+CD44+CD49f+ cells." (PMID 28487492, 2017). "Biocompatible and biodegradable HA-coated chitosan NPs were developed to encapsulate a chemotherapeutic drug (5-Fu) to enhance drug accumulation in tumor cells and to improve the agent’s antitumor efficiency by offering targeted drug delivery via CD44." (PMID 28068992, 2017). "In our experiment, control tumours displayed a significantly stronger expression CD24+/CD44+ cells than tumours with down-regulation of Six1." (PMID 28388884, 2017). "The interaction of MMP2 and CD44 is an important factor in selectively regulating the tumor microenvironment to promote tumor cell metastasis and is considered to be an inducer of EMT." (PMID 28679402, 2017). "In MPM, the presence of HA and its receptor, CD44 have been shown to facilitate neoplastic cell motility and invasion linking CD44/HA interactions in tumor progression." (PMID 28403901, 2017). "Many of the downstream pathways following CD44 activation become deregulated in cancer, leading to tumor growth, progression and metastasis." (PMID 28212584, 2017). "In conclusion, we demonstrated the role of CD44 expressed on fibroblasts in tumour microenvironment." (PMID 28523716, 2017). "Although CD24 was excluded from the analysis since it was expressed by most tumor cells in our ascitic effusion samples, CD44+CD117+ cells significantly overexpressed NANOG, SOX2 and OCT4, compared with the negative counterpart CD44+CD117−." (PMID 28726781, 2017). "An anti-CD44 antibody prevented CD90+ CD44+ CSC-mediated tumor formation both locally and systemically." (PMID 28137313, 2017). "In the tumor tissues, the cell surface marker of CSCs (CD44) was significantly depleted after VEDT treatment compared with vehicle as analyzed by both immunostaining and Western blot analyses." (PMID 28404939, 2017). "Through binding of CD44, HA can activate cytoskeleton and matrix metalloproteinases signaling involved in tumor progression." (PMID 29077041, 2017). "CUR was determined to reduce the expression of DCLK1/CD44/ALDHA1/LGR5/NANOG in CRC CSC three-dimensional spheroid cultures as well as in tumor xenografts." (PMID 28611316, 2017). "Based on enhanced gene copy number and gene expression, we identified CD44 upregulation as a major player in tumor cell aggressiveness and resistance to chemotherapy." (PMID 29371972, 2017). "The CD44 was described as a stem cell marker of various cancer stem cell populations and was involved in tumor progression and metastasis." (PMID 28930164, 2017). "The correlation between CD44 expression and c-Met expression bring us that the migration activity of CD44 expressing stem cells would lead tumor invasion and metastasis." (PMID 29069721, 2017). "We also demonstrated that PDE3A was strongly overexpressed in CD44+ cells in the tumor tissues of PDAC patients." (PMID 28507327, 2017). "PL21 showed a focal amplification in chromosome 6 and 17 of the primary tumor, which was also seen in unsorted cells and in the CD44+/CD24-/low subpopulation." (PMID 28423035, 2017). "Our IF and cytometry data also revealed that AMHR2 is expressed by a fraction of tumor cells, especially those that are positive for E-cadherin and CD44, a cancer stem cell marker, in line with previous studies." (PMID 29245952, 2017).
tumor (continued). "In our study, the relative expression of CD44 and CD66c was 6.10 ± 0.07 and 2.42 ± 0.01, respectively, which indicates higher expression in tumor samples than in normal mucosa." (PMID 28604612, 2017). "We found a significantly increased CD44 expression on metastasized tumor cells in the lung and the liver of HTM and TM with trastuzumab treatment." (PMID 27835865, 2017). "The tumor and metastasis promoting function is mediated in part by HA binding to and subsequent activation of CD44." (PMID 28086235, 2017). "This nanoparticle was reported acquiring higher delivery rate and more efficient gene silencing activities in CD44+ (overexpressing) drug resistant tumor cells." (PMID 28785557, 2017). "CD44+ HNSCC cells are capable of initiating tumors that demonstrably replicate the original tumor heterogeneity in nude mice, as well as self-renewal after serial passaging in vivo." (PMID 27276062, 2016). "There was also membranous expression of the CSC marker CD44 (brown) that was exclusively localized to cells within the tumor nests." (PMID 27532037, 2016). "The cell surface protein CD44 modulates cellular signaling cascades important for tumor progression." (PMID 27650542, 2016). "Only the expression levels of CD133 and CD44 were higher in tumor tissues than in the peritumoral tissues of HCC patients by qRT-PCR." (PMID 27329727, 2016). "We have recently shown that blocking CD44-binding to HA with RG7356, an anti-CD44 antibody directed against the constant region of CD44, prevents tumor cell adhesion in vitro and leads to tumor growth inhibition in several in vivo xenograft models." (PMID 27463372, 2016). "In xenograft tumor model, miR-34a has been shown to negatively regulate the tumorigenic properties of high CD44 expression lung CSCs." (PMID 28074102, 2016). "HA binding to CD44 generates concomitant onset of multiple signaling pathways leading to tumor-specific behaviors and cancer progression." (PMID 27070574, 2016). "Further studies are needed to isolate the CD133+CD44+CD54+ cellular subpopulation from peripheral blood or tumor tissue of CRC patients, investigating the metastatic potential of this subpopulation by xenograft assay." (PMID 27764803, 2016). "Even in a tumor containing numerous cells positive for either CD44 or ALDH1, or possibly both, there were very few individual double-stained cells, less than 1% (arrows)." (PMID 27768764, 2016). "We compared the relative CD44 mRNA expression of patients with age, sex, smoking, tumor size, clinical and pathological LAP and 5 years survival rate." (PMID 28008391, 2016). "Immunohistochemistry staining and Western Blot showed that YM155 treatment inhibited expression of survivin and CD44, induced apoptosis and reduced CD44+ CSCs in xenograft tumor tissues in vivo." (PMID 26771139, 2016). "In the present study, the patients with double expression of MMP-14 and CD44 in their tumor had a poor prognosis." (PMID 27590006, 2016). "Our phototheranostic agent CD44-IR700 is expected to inhibit tumor growth and eliminate CD44-positive cell population by phototherapy in TNBC PDX models as long as CD44-overexpression is validated on the surface of patient-derived tumor cells." (PMID 27302409, 2016). "pSTAT3 (red) and membranous staining of CD44 (green) were co-expressed by cells within the tumor nests." (PMID 27532037, 2016). "In the tumor, epithelium close to the stroma shows positive staining for CD44 (A), whereas staining with vimentin (B) or E-cadherin (C) is negative at that site, this is indicated with arrows." (PMID 27590006, 2016). "About half of the identified upregulated genes (24/42 genes) have been shown to play a role in tumor development and progression (e.g. Cd44, Myc, etc.)." (PMID 27589228, 2016).
tumor (continued). "In line with loss-of-function assay, gain of CD24 function imparted more colony formation capacity in tumor sphere, soft agar assay, and therapeutic resistance in comparison with CD44 overexpression." (PMID 27521216, 2016). "CD44 is an adhesion molecule and a marker of CSCs that is expressed in several normal and tumor tissues." (PMID 26821610, 2016). "The ability of tumorigenesis and tumor metastasis indicated the stemness of HCC cells with CD44 expression." (PMID 27769048, 2016). "CD44 and Shh signaling are important biomarkers for tumour aggressiveness, survival, and recurrence in GC." (PMID 26839535, 2016). "In our xenograft mouse model, a 7-day continuous infusion of YM155 at 5 mg/kg induced massive tumor regression with decreased expression of survivin and CD44 in intratumoral." (PMID 26771139, 2016). "This sE-selectin-mediated pleiotropic effects result in enhancement of homing of CD44+/high BCs and immune cells to the lung and tumor, respectively." (PMID 27220365, 2016). "Knockdown of CD44 resulted in limited colony formation and reduced tumor formation in xenografts, strongly indicating a functional role of CD44 in CRC tumorigenesis." (PMID 27152521, 2016). "Our experiments also show elevated levels of CD44 expression in tumor cells, and P-selectin in washed platelets activated by Cat K in co-culture, corroborating the observed expression of these glycoproteins in metastatic tumor cells." (PMID 26931461, 2016). "Here, we provide evidence that one of the main cellular events following CD44-targeting results in macrophage-mediated phagocytosis of tumor cells." (PMID 27463372, 2016). "CD44+ cells have also exhibited a strong colony forming capacity and tumor growth in xenograft mouse models compared to CD44− cells." (PMID 27455311, 2016). "We observed that the HALNPs specifically target GBM cells over other brain cells due to higher expression of CD44 in tumor cells." (PMID 27120809, 2016). "In tumors generated by cells that were purely of the mPlum-expressing CD44+/β1+ phenotype, mPlum-expressing tumor cells consisted 27.5 ± 3.2% of the tumor mass (the rest are expected to be various stromal cells and leukocytes)." (PMID 27835603, 2016). "The subpopulation of breast CSCs is characterized by phenotype CD44+/CD24low/-, by their tumor-initiation capability in immune-compromised mice and by an in vitro ability to form mammospheres." (PMID 26934679, 2016). "In this study, we present evidence for tumor suppressive functions of miR-199a-3p in both purified CD44+ and bulk PCa cells based on in vitro clonogenic and in vivo tumor regeneration assays as well as therapeutic experiments." (PMID 27447749, 2016). "RG7356 has also demonstrated growth inhibition of several CD44-expressing tumor xenografts (Roche internal data)." (PMID 27507056, 2016). "More specifically, the use of magnetic nanoparticles such as superparamagnetic iron oxide nanoparticles (SPIONs) functionalized with HA has been investigated for targeting CD44-overexpressed tumor malignancies and inflammations." (PMID 27200096, 2016). "FACS analyses using the relevant antibodies demonstrated that out of these mPlum-expressing tumor cells, only 9.0 ± 2.9% retained the original phenotype of CD44+/β1+." (PMID 27835603, 2016). "In recent studies, CD44 has been recognized as a pleiotropic molecule related to tumor metastasis and aggressive behavior and has become an attractive target for antitumor theranostics." (PMID 27255899, 2016). "The second set of experiments was performed in a similar manner, but the tumor cell population that was sorted out was of CD44+/β1+ cells and the cells expressed mPlum." (PMID 27835603, 2016). "Significant reduction of CD44 expression and CD44+ population was observed in the tumor tissues of the MB109-IP250 group as compared to the Sham group." (PMID 27650540, 2016).
tumor (continued). "We have shown, that factors presented in pr.CM increase both the ALDH positivity and expression of CD24−/CD44+/EpCAM+ cell surface markers in tumor cells." (PMID 26759169, 2016). "In this study, we observed that the mRNA expression of CD133 and CD44 among 12 CSC markers in the tumor tissues of HCC patients was significantly different from that in peritumoral tissues." (PMID 27329727, 2016). "In this study, GSI exposure diminished the subpopulation of CD24+CD44+ in all CC cell lines and induced a significant reduction of anchorage-independent growth and delayed tumor engraftment in mice." (PMID 27821106, 2016). "Despite controversies regarding the existence of GCSCs, CD44 has been used as a marker for enriching cancer stem cells (CSC) or tumor-initiating cells in many cancer types including breast cancer, GC, pancreatic adenocarcinoma, and hepatocellular carcinoma." (PMID 27107424, 2016). "The detection of a EMA+/CD44+/SOX2+/OCT4+/SALL4+/pSTAT3+/NANOG+ subpopulation within the tumor nests aligns with recent literature reporting localization of CSC in OCSCC, particularly at the “tumor front”." (PMID 27532037, 2016). "Then, we tested the protein expression of CD133 and CD44 in clinical HCC tumor tissues and observed that higher expression of each marker (3 or more using IHC scoring system) had a poorer impact on the survival time of patients." (PMID 27329727, 2016). "OPN is a secreted glycophosphoprotein that acts a ligand for its receptors, including integrins and CD44 variants, and the interactions between OPN and its receptors promote a variety of signaling pathways that eventually result in tumor progression." (PMID 27888617, 2016). "Bahnassy and colleagues have shown that aberrant expression of cancer stem cell markers (CD133, CD90 and CD44) contributes to tumor progression." (PMID 27244897, 2016). "The recurrence-free survival time of patients with CD44-positive tumours was lower than that of patients with CD44-negative tumours (39.0% versus 79.5%, resp., P = 0.001)." (PMID 26839535, 2016). "Stem cells markers CD44 and Nestin were decreased in tumour samples from mice treated with vincristine combined with MRS1220, compared to the vehicle group." (PMID 27634913, 2016). "CD44 is one of the most important CSC markers for its role in promoting tumour metastasis and invasion." (PMID 27825361, 2016). "Hyaluronidase possibly acts by degradation of mesothelial-associated hyaluronan, thereby preventing hyaluronan from interacting with CD44 on tumour cells." (PMID 27074785, 2016). "We further demonstrated, for the first time, that the degree of hypoxia-induced CSC-sphere formation (CD44+ subpopulation) in vitro and of tumor metastasis/dissemination in vivo were markedly suppressed by knocking down Id2 expression." (PMID 26965643, 2016). "A sequence in the hemopexin domain of MMP-9 (PEX9) impairs tumor cell adhesion to PEX9/MMP9 through interaction with CD44." (PMID 26869928, 2016). "We further demonstrated, for the first time, that hypoxia-induced CSC sphere formation (CD44+ subpopulation), and the expression of stem-cell markers in vitro and tumor metastasis/dissemination in vivo were markedly suppressed by knocking down Id2 expression." (PMID 26965643, 2016). "We noted a tendency of higher CD44 expression in high-grade tumors compared to low grade, so it can serve as tumor behavior indicator." (PMID 26821610, 2016). "As one of the variant forms of CD44, CD44V6 has been noted to associate with cell adhesion, proliferation, differentiation, and survival and are thereby prone to be involved in tumor progression." (PMID 27809879, 2016). "Infiltrating TAMs also enhanced tumor-initiating properties of CD44+ALDH1+ pancreatic CSCs by activating STAT3 signaling." (PMID 26980947, 2016). "CD44v isoforms are expressed in both normal and tumor cells at different levels, indicating that the CD44 isoforms are also an essential component for normal cellular functions." (PMID 27200096, 2016).
tumor (continued). "EZH2 knockdown significantly reduced the CD133+/CD44+ subpopulation, suppressed mammosphere formation, and decreased the expression of self-renewal-related genes and strongly impaired tumor-initiating capacity in a re-implantation mouse model." (PMID 27172794, 2016). "Tumours with high CD44, Shh, and Gli1 expression had more cases of advanced tumour invasion, an increased likelihood of lymph node metastasis, advanced TNM stage." (PMID 26839535, 2016). "CD44 is a well-established cancer stem cell marker playing a crucial role in tumor metastasis, recurrence and chemo-resistance." (PMID 27521214, 2016). "Taken together, these results indicate that CD44 overexpression antagonizes SALL4 knockdown-mediated inhibition of tumour growth in vivo." (PMID 27819668, 2016). "Unfortunately, we failed to see full immunity in the mice after adoptive transfer, probably due to the highly aggressive and rapid proliferative nature of 4T1 tumor cells and failure in sorting of CD44+ T cells for adoptive transfer." (PMID 27853305, 2016). "p63 has been shown to increase the expression of tumor promoting genes/factors like CD44, COX2, and β catenin." (PMID 27584160, 2016). "More shortened survival time was observed in the group with double high expression of CD133/CD44, as well as in the tumor-bearing animals." (PMID 27329727, 2016). "CD44 is a highly glycosylated transmembrane protein and is expressed in a variety of epithelial and mesenchymal cells as well as tumor cells." (PMID 27482895, 2016). "Just as normal stem cells divide to give rise to identical stem cells and a diverse group of differentiated cells, CD44+ cells can self-replicate in addition to producing the gamet of tumor stromal cells." (PMID 26907349, 2016). "Immediately after three days of TME Stimulation, 41 ± 17.4% and 18.7 ± 6.3% of tumor cells were characterized by the CD44+/β1+ and CD44+/CD24low/− phenotypes, respectively." (PMID 27835603, 2016). "A higher proportion of high-grade tumor tissues showed moderate or strong CD44 staining compared to low-grade tumors." (PMID 26821610, 2016). "miR-199a-3p overexpression also diminished tumor-initiating capacities of CD44+ PCa cells as well as tumor regeneration from bulk PCa cells." (PMID 27447749, 2016). "The differentiated APL cells derived from the excised tumor mass exhibited decreased CD44 expression in fucoidan+ATRA treated mice." (PMID 27329592, 2016). "To identify CD44 transcripts that segregate with mitogenic or tumor-related activities, we first adapted DJM-1 cells, a SCC cell line, to serum-free condition, as we also used for NHKs." (PMID 27505250, 2016). "It is clear for the success of drugs targeted at CD44 and RHAMM it is important to identify the subset of patients whose tumor are highly dependent on CD44 and RHAMM for growth." (PMID 27595989, 2016). "CD44 attracted considerable interest for its abundant expression on CSCs, and overexpressed in local tumor tissues promoting tumor progression." (PMID 27769048, 2016). "CD44 standard (CD44s) is required for tumor growth, metastasis, and post-radiation recurrence of pancreatic xenograft tumors in mice." (PMID 27107424, 2016). "LMP1 activated and triggered phosphoinositide 3-kinase/protein kinase B (PI3K/AKT) pathway, which subsequently stimulated expression of CD44, development of side population and tumor sphere formation." (PMID 28050219, 2016). "CD44 is the most commonly used cell-surface marker for CSCs across multiple tumor types and has been consistently acknowledged as CSC marker in HNSCC." (PMID 26880935, 2016). "Immunofluorescence (IF) staining verified a substantial KD of FGFR2 or CD44 following oral administration of Dox during tumor growth in tumor cell-injected mice and a subsequent delay in tumor growth (respectively)." (PMID 27107424, 2016).